STIL (STIL centriolar assembly protein)
Diseases named in the same sentence as STIL in open-access papers (continued):
Sharing a sentence is not in itself a finding about the gene and the disease.
skin cancer (2 papers, 2022 to 2024).
Astrocytoma (1 paper, 2022). "Consistent results were also found in GEO datasets, in BLCA, Astrocytoma, SKCM, LUAD, BRCA, and Glioma, patients with high STIL expression showed worse prognosis." (PMID 35155425, 2022).
Atrophy (1 paper, 2025). Any weakening or degeneration, especially through lack of use. "Extratumoral parenchymal signs were found to be an independent predictor for sTIL levels (OR = 0.64, p < 0.001), with a negative correlation observed between the contraction sign and sTIL levels (p < 0.001, r = −0.185), as well as between the atrophy sign and sTIL levels (p=0.046, r = −0.103)." (PMID 40599582, 2025).
Bardet-Biedl syndrome 12 (1 paper, 2021). Any Bardet-Biedl syndrome in which the cause of the disease is a mutation in the BBS12 gene. "These variations were present in genes BBS12, STIL, COG6 and PIEZO1.A mutation in BBS12 causes Bardet-Biedl syndrome 12 (OMIM #615989)." (PMID 33772059, 2021).
bladder tumour (1 paper, 2023). "In the other two datasets from the GEO and oncomine database, the STIL mRNA expression was also up-regulated in the tumour, especially the muscle-invasive bladder cancer (MIBC) and recurrence bladder tumour." (PMID 37101292, 2023).
invasive carcinoma (1 paper, 2020). A carcinoma that is not confined to the epithelium, and has spread to the surrounding stroma. "In areas of non‐invasive papillary urothelial carcinoma, but not invasive carcinoma, sTIL levels were found to be significantly associated with DFS." (PMID 32374509, 2020).
invasive ductal carcinoma (1 paper, 2020). "Higher sTIL level was also associated with age (< 50 years), race/ethnicity (black), histologic type (invasive ductal carcinoma), and histologic grade (grade 3) in the ER/PR positive group without NACT, and with age (< 50 years) in the HER2 group without NACT." (PMID 32576238, 2020). "In addition, higher sTIL level was associated with age (< 50 years), race/ethnicity (black), histologic type (invasive ductal carcinoma), and HER2 status (positive) in the subgroup without NACT and with tumor size (smaller tumor) in the subgroup with NACT." (PMID 32576238, 2020).
kidney cancer (1 paper, 2022). Primary or metastatic malignant neoplasm involving the kidney. "Moreover, STIL silencing could promote primary cilia formation and inhibit cell cycle protein expression in prostate and kidney cancer cell lines." (PMID 35155425, 2022).
liver cancer (1 paper, 2025). An epithelial or non-epithelial malignant neoplasm that arises from the liver. "Furthermore, the STIL expression was considerably upregulated in human liver cancer cell lines as opposed to normal liver cells." (PMID 39718123, 2025).
melanoma (1 paper, 2022). A malignant, usually aggressive tumor composed of atypical, neoplastic melanocytes. "To this end, we induced centrosome amplification by overexpression of key regulators involved in the centrosome duplication cycle, namely, PLK4 and STIL, in noninvasive melanoma cells that show otherwise no aberrant centrosome numbers." (PMID 36875714, 2022).
papilloma (1 paper, 2024). A benign epithelial neoplasm that projects above the surrounding epithelial surface and consists of villous or arborescent outgrowths of fibrovascular stroma. "Despite STIL overexpression-induced centrosome amplification in both basal and suprabasal epidermal cells, papilloma formation was reduced in this system." (PMID 39466849, 2024). "Importantly, STOP cassette excision was found in only about one third of the papillomas from tamoxifen-treated K14CRE-ERT2-STIL+/- mice, indicating that the majority of these papillomas originated from epithelial cells, which escaped activation of STIL transgene expression." (PMID 39466849, 2024).
renal cell carcinoma (1 paper, 2023). "According to CTRP drug sensitivity analysis, high level of CBX2, BLNK, PLK4, STIL and BIRC5 were associated with increased sensitivity to inhibitors of VEGF and MET pathways, which happened to be two crucial driver pathways of renal cell carcinoma." (PMID 37917664, 2023).
skin papilloma (1 paper, 2024). A benign papillary neoplastic growth on the skin composed of epithelial cells and a fibrous stalk.
T-cell leukemia (1 paper, 2018). A malignant disease of the T-lymphocytes in the bone marrow, thymus, and/or blood. "Interestingly, STIL protein was shown to be heavily deregulated in T-cell leukemias through genome modifications leading to gene fusions." (PMID 29370181, 2018).
testis cancer (1 paper, 2024). "Almost all of the top-performing genes were that of over-expression, with PMS2 in THYM; CARD11, LASP1, STIL, POLE, KMT2C, and CLIP1 in testis cancer; ERC1, WRN, OLIG2, FANCC, and ACSL6 in ACC; and SOX2 and NDRG1 in ESCA leading in performance with AUCs ranging 0.832-0.911." (PMID 38491101, 2024).
thyroid cancer (1 paper, 2022). "Increased STIL mRNA levels were also observed in various other types of cancers, including breast, prostate, uterine, kidney, head and neck, liver, bladder, colon, and thyroid cancers, where it was also associated with poor overall survival." (PMID 35365182, 2022).
tumor (41 papers, 2018 to 2025). "STIL centriolar assembly protein (STIL) is a cytoplasmic protein implicated in cellular growth and proliferation as well as chromosomal stability, which abnormal condition affected tumor immunity and tumor progression." (PMID 36899391, 2023). "Though silencing STIL expression to control STIL reach to specific levels instead of absolute loss not only promote PC formation but inhibit tumor progression." (PMID 37101292, 2023). "We observed that the levels of STIL expression were positively associated with tumor purity (cor = 0.144, P = 7.13e−03), indicating STIL expression was found mainly from the tumor cells." (PMID 36899391, 2023). "Combined with our current findings on CIN/CNAs associated with STIL overexpression via centrosome amplification in NSCLC, we hypothesize that STIL overexpression is strongly linked to malignant tumor progression, tumor heterogeneity, and drug resistance." (PMID 39727708, 2024). "Therefore, we investigated the association between STIL expression and the tumor-infiltrating immune cells in HCC using the TIMER database." (PMID 36899391, 2023). "The significantly higher sTIL percentage in premenopausal and younger women might be linked to these tumor features, which are more frequent in this population." (PMID 37345183, 2023). "Also, the expression levels of STIL were positively associated with the tumor-infiltrating immune cells and its marker genes in HCC." (PMID 36899391, 2023). "The presence of sTIL was also associated with features of increased biological aggressiveness, such as grade 3, increased proliferation, increased nodal involvement and larger tumor size." (PMID 37345183, 2023). "Silencing STIL can inhibit tumor metastasis and growth, while overexpression of STIL triggers the epithelial‐to‐mesenchymal transition (EMT) pathway, enhancing cancer cell invasion and migration." (PMID 39718123, 2025). "It has been confirmed that STIL is abnormally overexpressed in various tumors, regulating tumor progression." (PMID 39718123, 2025). "As a critical marker of the tumor microenvironment, sTIL level has demonstrated a strong correlation with tumor response to NAC in BC." (PMID 40917012, 2025). "Because the tumor progression is attributed to the presence of CSCs, studies have proved that STIL is involved in regulating cancer cell stemness." (PMID 39718123, 2025). "This study aimed to examine the regulatory mechanisms and the function of STIL in the stemness of HCC tumor cells." (PMID 39718123, 2025). "As the median lifespan of CMV-STIL mice is reduced below the mean age of tumor diagnosis, we conclude that STIL-transgenic mice likely developed fewer tumors because they died from other reasons before having reached the typical age of tumor onset." (PMID 39466849, 2024). "In NSCLC, STIL overexpression has been documented and its role in tumor metastasis has been suggested through mechanisms beyond centrosome amplification." (PMID 39727708, 2024). "STIL knockdown has been shown to suppress malignant characteristics such as tumor proliferation, migration, invasion, and metastasis in cancers of the lung, colorectum, bladder, liver, and breast." (PMID 39727708, 2024). "Collectively, these results showed that STIL was highly expressed in tumor tissue, high-STIL expression predicts poor OS, and was significantly associated with HCC cell proliferation, invasion, and migration." (PMID 36899391, 2023). "In differential analysis, the expression of STIL protein was significantly upregulated in tumor tissue compared with adjacent normal tissue." (PMID 36899391, 2023). "In the TCGA-BLCA dataset, STIL mRNA expression was up-regulated in tumour tissue, and the patients with high STIL expression showed a worse prognosis." (PMID 37101292, 2023). "In our previous study, STIL is up-regulated in tumor tissues and is closely related to the bad prognosis of patients." (PMID 37101292, 2023).
tumor (continued). "Dysregulated STIL is exert a crucial function in chromosomal instability which is found to be involved in the tumor immune microenvironment." (PMID 36899391, 2023). "Our collective in vitro and in vivo results on cell proliferation, colony formation, and xenograft tumor assay support a role of STIL in tumor progression." (PMID 35365182, 2022). "To explore the relationship between tumor progression, prognosis, and STIL expression, we collected the clinical data from the TCGA database." (PMID 35155425, 2022). "The strength of our study lies in the use of multiple tumour zones to analyse the variations of sTIL and Treg cell distribution within different tumour zones." (PMID 36552993, 2022). "In the present studies, we identify a novel STIL-mediated mechanism that promotes tumor progression and metastasis." (PMID 35365182, 2022). "A remaining open question is: Do the extra centrosomes induced by excess STIL promote tumor initiation and drive spontaneous tumorigenesis?" (PMID 35365182, 2022). "We further demonstrated that a subset of STIL translocate into nucleus and associate with FOXM1 to promote tumor metastasis and CS via FOXM1-mediated downstream target genes." (PMID 35365182, 2022). "To explore the effects of STIL on proliferation in vivo, we used a xenograft model and confirmed that STIL knockout inhibited the growth of xenograft tumor cells." (PMID 36497260, 2022). "A subset of STIL translocate into nucleus and associate with FOXM1 (Forkhead box protein M1) to promote tumor metastasis and stemness via FOXM1-mediated downstream target genes." (PMID 35365182, 2022). "In this study, we unmasked for the first time that STIL expression was up-regulated in most tumor tissues than that in the adjacent normal tissues." (PMID 35155425, 2022). "Our experimental results show that STIL has similar results in BC: STIL knockout inhibited BC cells proliferation and migration in vitro and blocked proliferation of tumor in vivo." (PMID 36497260, 2022). "To understand the role of STIL in proliferation and tumor growth of CRC, we stably silenced STIL gene in HT-29 CRC cells using shRNA." (PMID 34485108, 2021). "Our study substantiates a novel role for STIL in regulation of tumor growth, drug resistance, and stem cells in CRC." (PMID 34485108, 2021). "In lung cancer, upregulation of STIL has been reported to have significant effect on tumor mitotic activity." (PMID 34485108, 2021). "Being a regulator of cell proliferation, its role in cancer becomes obvious, and many tumor types have been reported to have enriched expression of STIL." (PMID 34485108, 2021). "Chi-square analysis revealed that females (69.4%) and early-stage tumor (73.3%) correlated well with higher expression of STIL with a p value of 0.04 and 0.03, respectively." (PMID 34485108, 2021). "Further, we analyzed nuclear expression of the proliferation marker Ki-67 in tumor xenograft tissue and found a significantly reduced expression in STIL-silenced group compared to control (p=0.01)." (PMID 34485108, 2021). "Further studies with STIL-silenced xenograft showed a remarkable difference in tumor growth in NOD/SCID mice with lesser tumor volume and weight compared to control shRNA group." (PMID 34485108, 2021). "We discovered that STIL may enhance tumor stemness by stimulating the glycolysis pathway of HCC cells through cell functional experiments." (PMID 39718123, 2025). "Beyond tumor boundaries, we further observed that extratumoral parenchymal structural abnormalities, particularly the contraction sign, were the strongest imaging predictors of reduced sTIL levels." (PMID 40599582, 2025). "In contrast, sTIL expression showed greater variability among different tumor sections." (PMID 40861467, 2025).
tumor (continued). "IHC experimental results indicated that knocking down RFX5 significantly inhibited the protein expression of RFX5 and STIL in tumor tissues, while further overexpression of STIL reversed the inhibitory effect of RFX5 knockdown on STIL protein expression without affecting RFX5 protein expression." (PMID 39718123, 2025). "The miR-18a/low tumours had higher expression of the luminality-associated genes like ESR1, GATA3, FOXA1, XBP1 and TFF1 and a lower expression of the basality-associated genes such as KRT18, KRT17, FOXC1, ANLN, STIL and MIA (p < 0.05)." (PMID 38786043, 2024). "The primary reason for this may be that TNBC patients with enriched sTIL expression tend to have stronger anti-tumor immune capabilities." (PMID 39286481, 2024). "So balancing STIL expression is essential for primary cilia existence and tumor growth." (PMID 37101292, 2023). "STIL down-regulation decreased the xenograft tumour volume compared to the control group." (PMID 37101292, 2023). "However, the relationship between STIL and tumor immunity and its expression pattern, clinical outcomes, and potential regulatory pathway in HCC progression remains determined." (PMID 36899391, 2023). "SCL/TAL1 interrupting locus (STIL), a PC-related protein, was screened in our previous study and could influence the cell cycle by regulating PC in tumor cells." (PMID 37101292, 2023). "The balance of PC-related protein STIL is essential for tumor and signalling pathways." (PMID 37101292, 2023). "Furthermore, Tumour growth and weight ratios (weight of tumour/weight of mouse) of the STIL silenced group showed slower than that of the vector-transfected group." (PMID 37101292, 2023). "In luminal B BC, prior works have shown that genomic signatures related to tumor inflammation or BRCA-related DNA repair deficiency may also predict endocrine resistance and immune evasion, even in the presence of high sTIL." (PMID 37345183, 2023). "In addition, through dynamic observation of tumor growth, it was found that the tumor growth of the STIL knockout cells was slowed." (PMID 36497260, 2022). "Within the tumour, we found higher sTIL and Treg cell proportions in the TP than in the TC." (PMID 36552993, 2022). "Nevertheless, in READ and THYM, high STIL expression may prevent patients from death and tumor recurrence." (PMID 35155425, 2022). "Since STIL is a master regulator of PLK4, we speculate that a low-to-moderate level of STIL could promote tumor initiation, as seen for PLK4, via a yet-unknown mechanism." (PMID 35365182, 2022). "Moreover, STIL knockout markedly blocked proliferation and migration of BC cells in vitro and inhibited proliferation of tumor in vivo, and triggered cell cycle arrest in the G0/G1 phase." (PMID 36497260, 2022). "Among them, STIL showed the highest T/N ratio (3.5-fold increase), suggesting that it might play a unique and significant role in tumor development." (PMID 35365182, 2022). "However, sex-adjusted binary regression analysis revealed that higher tumor stage has 71% lesser chance of high expression of STIL compared to early stage (p value 0.02), and earlier association of female sex with STIL expression was influenced by tumor stage." (PMID 34485108, 2021). "Summarizing, immunohistochemically detected SASP in tissues was significantly associated with tumor aggressiveness (LVI, high histologic grade, and triple-negativity) and with immune microenvironments exhibiting high sTIL density and iCD103 + lymphocyte infiltration." (PMID 34267603, 2021). "Put together, these results suggest that overexpression of STIL in CRC could have crucial unexplored role in tumor development and disease progression." (PMID 34485108, 2021). "STIL silencing reduced proliferation and tumor growth in CRC." (PMID 34485108, 2021). "The STIL expression was up‐regulated in GC compared with that in adjacent non‐tumor tissues." (PMID 31187582, 2019).